TCF7L2 (transcription factor 7 like 2)
Diseases named in the same sentence as TCF7L2 in open-access papers (continued):
Sharing a sentence is not in itself a finding about the gene and the disease.
Glucose intolerance (continued). "We demonstrate that overexpression of Tcf7l2 in the multiple tissues where it is normally expressed leads to glucose intolerance, but reducing Tcf7l2 expression to wild-type levels in beta cells while maintaining overexpression elsewhere increases the severity of the glucose intolerance phenotype." (PMID 25398947, 2015). "Glucose intolerance was also apparent in TCF7L2 +/− mice compared with control (top)." (PMID 23028378, 2012). "Glucose intolerance was observed in TCF7L2-knockdown mice compared with control, suggesting that insulin signaling might be perturbed with acute depletion of TCF7L2 in mice." (PMID 23028378, 2012). "Knockdown of hepatic TCF7L2 promoted increased blood glucose levels and glucose intolerance with increased gluconeogenic gene expression in wild-type mice, in accordance with the PCR array data showing that only the gluconeogenic pathway is specifically up-regulated upon depletion of hepatic TCF7L2." (PMID 23028378, 2012). "Importantly, none of the mice were diabetic during behavioral testing as we previously reported glucose intolerance in mice overexpressing Tcf7l2 only after a high fat diet stress." (PMID 22046400, 2011). "Similarly, the emergence of glucose intolerance with age in βVps13cKO mice, which is reminiscent of changes seen after the inactivation of the T2D GWAS gene Tcf7l2 in mice, seems to reflect, at least in part, increasing insulin resistance as well as impaired insulin output from the pancreas." (PMID 27329800, 2016). "Significant upregulation of TCF7L2 gene expression in VAT that correlates with PPTg and glycaemia is also seen in Asian Indians with glucose intolerance." (PMID 36263318, 2022). "The observation that alpha cell mass was not altered in mice with beta cell-specific deletions in Tcf7l2 and glucose intolerance suggests that the increase in this variable in risk allele carriers may be due to a cell-autonomous role for TCF7L2 in the alpha cell." (PMID 28343277, 2017). "- Genotypic and allelic frequencies and estimates of relative risks for the rs7903146 polymorphic form of TCF7L2 gene in subjects with and without glucose intolerance." (PMID 36263318, 2022). "The role of TCF7L2 extends to non-pancreatic tissues, a recent study that revealed that TCF7L2 overexpression in non-pancreatic tissues leads to worsened glucose intolerance, and that the function of TCF7L2 in maintaining glucose metabolic balance in peripheral tissues may be more robust." (PMID 29713286, 2018). "Interestingly, the persistent overexpression of Tcf7l2 in non-pancreatic tissues results in a significant worsening in glucose tolerance in vivo, indicating that Tcf7l2 overexpression in beta cells does not account for the glucose intolerance in the Tcf7l2 overexpression mouse model." (PMID 25398947, 2015).
gestational diabetes (19 papers, 2016 to 2025). Carbohydrate intolerance first diagnosed during pregnancy. "In pregnant women, the TCF7L2 gene and its related TCF7L2 rs790314 C>T polymorphism are correlated with a higher risk of gestational diabetes mellitus (GDM)." (PMID 38474710, 2024). "The TCF7L2 variants (such as rs7903146 and rs12255372) are associated with the pathophysiology of gestational diabetes mellitus (GDM), T1D, latent autoimmune diabetes of adults (LADA), and T2D." (PMID 37941991, 2023). "It is reported that even after adjusting for confounding factors such as BMI and age, the T risk allele in TCF7L2 rs7903146 is associated with early postprandial glucose control failure and insulin treatment needs in women with gestational diabetes." (PMID 36339414, 2022). "Association between TCF7L2 rs7903146 polymorphisms and risk of gestational diabetes mellitus in overall sample and in sub-racial groups." (PMID 27058589, 2016). "TCF7L2 is an extensively studied genetic factor implicated in reduced insulin secretion and an increased risk of developing gestational diabetes mellitus (GDM)." (PMID 38694942, 2024). "For example, our group, by using a simple panel of nine nutrigenetic variants, demonstrated an increased risk of gestational diabetes mellitus (GDM) in women carriers of the TT genotype of the TCF7L2 gene (OR 2.5)." (PMID 32290086, 2020). "Also, rs7903146 (C/T) TCF7L2 variant is accompanied by a high probability of developing insulin-dependent gestational diabetes mellitus (ID-GDM)." (PMID 38612849, 2024). "Recent studies have found that single nucleotide polymorphisms (SNPs) in TCF7L2, CAPN10, KCNQ1, and ADIPOQ are associated with the onset of gestational diabetes." (PMID 38166877, 2024). "Out of the individuals with the TCF7L2 risk variation, 33 tested positive and 19 tested negative for gestational diabetes, with a significant p-value of 0.012." (PMID 39469345, 2024). "The association between TCF7L2 and CAPN10 gene polymorphisms and gestational diabetes mellitus (GDM) has been explored in diverse populations across different geographical regions." (PMID 38166877, 2024). "However, a previous case-control study focused on the relationship of TCF7L2 rs290481 T>C polymorphism with gestational diabetes mellitus (GDM) in a Chinese Han population and suggested that this polymorphism was not a potential clinical value for the prediction of GDM." (PMID 29100364, 2017).
Hypertension (17 papers, 2006 to 2025). The presence of chronic increased pressure in the systemic arterial system. "Haplotype analysis of ADRB1, PTRD, TCF7L2 gene variants among hypertension patients and healthy controls." (PMID 38935682, 2024). "TCF7L2 rs4506565 has showed that the recessive model showed significant association (P = 0.042) with the development of hypertension." (PMID 38935682, 2024). "This study aimed to investigate the prevalence of polymorphisms NOS3; rs1799983, IGFBP3; rs11977526 and TCF7L2; rs7903146 in Brazilian women of African descent and their association with hypertension." (PMID 34001234, 2021). "Associations with hypertension were statistically significant, except for the TCF7L2; rs7903146 polymorphism, after adjusted analysis." (PMID 34001234, 2021). "Second, we found that the TCF7L2 rs7903146 is related to higher risk of retinal AV nicking only in Caucasians who had hypertension (P = 0.03)." (PMID 20478041, 2010). "TCF7L2 is a well-established susceptibility gene for type 2 DM, and given the high comorbidity rate and possibly shared pathophysiology between DM and hypertension, further studies into this target may be warranted." (PMID 35213968, 2022). "Moreover, potential effects of hypertension on the association of TCF7L2 gene and retinopathy have been largely unexplored." (PMID 20478041, 2010). "The less frequent genotypes of the NOS3, rs1799983, TCF7L2 rs7903146, and IGFBP3 rs11977526, SNPs were associated with a higher prevalence of hypertension in comparison with the ancestral and heterozygous genotypes." (PMID 34001234, 2021). "For TCF7L2; rs7903146 SNP, hypertension among women with CC, CT and TT genotypes had prevalences of 27.9%, 32.9% and 38.9%, respectively, with no statistical difference between TT and CC (PR = 0.86; 95% CI 0.69–1.06; p = 0.166)." (PMID 34001234, 2021). "The SNPs in the NOS3 rs1799983, IGFBP3 rs11977526, and TCF7L2 rs7903146 genes can directly influence the protein expression in the respective genes, making them important biomarkers for the development of hypertension." (PMID 34001234, 2021). "Our models identified TCF7L2 as a potential target for hypertension." (PMID 35213968, 2022). "However, although several studies have demonstrated a relationship between the TCF7L2 gene and DM, its relationship with the prevalence of arterial hypertension and oxidative stress has not been investigated." (PMID 34001234, 2021). "In addition, a study of the Thai elderly population suggested that the SNP rs290487 in TCF7L2 may contribute to risks of hypertension regardless of type 2 DM." (PMID 35213968, 2022).
Impaired glucose tolerance (17 papers, 2007 to 2025). An abnormal resistance to glucose, i.e., a reduction in the ability to maintain glucose levels in the blood stream within normal limits following oral or intravenous administration of glucose. "In fact, TCF7L2‐T2D variants confer the greatest relative risk for T2D, unquestionably predicting conversion to T2D in individuals with impaired glucose tolerance." (PMID 34612510, 2022). "As TCF7L2 is the gene predisposing to the greatest T2D‐relative risk, it predicts, in individuals with impaired glucose tolerance, conversion to T2D." (PMID 34612510, 2022). "It has been reported that overexpression of a nuclear isoform of Tcf7l2 (mice ortholog) in high-fat diet fed mice improves glucose tolerance, while depletion of Tcf7l2 in mice causes higher glucose levels and impaired glucose tolerance." (PMID 34492009, 2021). "In adults, the TCF7L2 rs7903146 T allele, commonly associated with type 2 diabetes (T2D), has been also associated with a lower body mass index (BMI) in T2D individuals and with a smaller waist circumference in subjects with impaired glucose tolerance." (PMID 17593304, 2007). "Mice overexpressing Tcf7l2 either in multiple tissues or specifically in the liver display impaired glucose tolerance." (PMID 25398947, 2015). "Fourth, as polymorphisms within TCF7L2 possibly impair the glucagon like peptide-1 induced insulin secretion, which in turn could lead to a lower postprandial insulin secretion, we might expect to see a stronger effect among patients with impaired glucose tolerance." (PMID 20478041, 2010). "Similarly, Tcf7l2-knockout mice also showed increased blood glucose levels and impaired glucose tolerance." (PMID 35874808, 2022). "Furthermore, mice with global haploinsufficiency of TCF7L2 exhibited higher glucose levels and impaired glucose tolerance compared with the littermate control, and adenovirus-mediated two-fold expression of TCF7L2 almost completely reversed the phenotype." (PMID 23028378, 2012). "Finally, haploinsufficiency of TCF7L2 in mice displayed higher glucose levels and impaired glucose tolerance, which were rescued by hepatic expression of a nuclear isoform of TCF7L2 at the physiological level." (PMID 23028378, 2012). "Furthermore, TCF7L2 haploinsufficiency promoted higher glucose levels with impaired glucose tolerance and increased hepatic glucose production in mice, and adenovirus-mediated TCF7L2 expression in the liver reversed the phenotype." (PMID 23028378, 2012). "A further limitation of the present study is the lack of examination of a potential role for incretins in the impaired glucose tolerance observed in mice lacking TCF7L2 in adipocytes." (PMID 33068125, 2021).
pancreatic cancer (16 papers, 2012 to 2026). "Aligning with our findings, the research conducted by Xiang and colleagues demonstrated an upregulation of TCF7L2 in pancreatic cancer, which was associated with enhanced tumour cell proliferation." (PMID 38769659, 2024). "Upstream activators associated with WNT signaling in CF centroacinar cells included enhanced expression of LEF1 and TCF7L2 relative to WT centroacinar cells, which are known to be associated with enhanced proliferation in pancreatic cancer." (PMID 39687022, 2024). "Pancreatic cancer patients with a high expression of TCF7L2 have a poorer prognosis than those with low expression levels, and the underlying mechanism is that TCF7L2 positively regulates aerobic glycolysis through the EGLN2/HIF‐1α axis." (PMID 34609082, 2021). "Transcription factor 7-like 2 (TCF7L2), one of the strongest genetic determinants of T2DM, has specific variants that are also associated with an increased risk of pancreatic cancer." (PMID 41601937, 2026). "In primary human pancreatic cancer cells, both mRNA and protein expressions of Gαi3 were significantly decreased following the silencing of TCF7L2, whereas ectopic overexpression of TCF7L2 led to an increase in Gαi3 expression." (PMID 39349432, 2024). "There is an increased binding between Gαi3 promoter and the transcription factor TCF7L2 in pancreatic cancer tissues and cells." (PMID 39349432, 2024). "Since KLF5 and TCF7L2 have been shown to be upregulated in pancreatic cancer stem cells, it would be interesting to validate if GALNT3 and B3GNT3 are driven by any of these TFs." (PMID 34367349, 2021). "For instance, transcription factor 7-like 2 (TCF7L2) is one transcriptional partner of the Wnt/β-catenin pathway regulating aerobic glycolysis in pancreatic cancer, which showed significantly lower dimethylation in PANC-1 cells in our quantitative proteomics." (PMID 33344439, 2020). "Inhibiting HATs in pancreatic cancer affected the activation of a certain subset of enhancers that are enriched by the Wnt-signaling transcription factor, Transcription Factor 7 Like 2 (TCF7L2)." (PMID 31067678, 2019). "To explore the potential relationship between TCF7L2 and glucose metabolism in pancreatic cancer, we used Seahorse XF Extracellular Flux Analyzers to analyze the effect of TCF7L2 on aerobic glycolysis." (PMID 29476053, 2018). "In the present study, we investigated the clinicopathological significance of TCF7L2 in pancreatic cancer." (PMID 29476053, 2018). "Then, we performed CCK-8 proliferation assays to validate the influence of TCF7L2 on pancreatic cancer viability." (PMID 29476053, 2018). "We performed a Kaplan–Meier analysis stratified by TCF7L2 expression, and we further detected and analyzed the TCF7L2 expression status and prognosis in patients with pancreatic cancer from FUSCC." (PMID 29476053, 2018). "In summary, we identified novel predictive markers for prognosis and suggest a previously unrecognized role for TCF7L2 in control of aerobic glycolysis in pancreatic cancer." (PMID 29476053, 2018). "To further validate this finding, we examined TCF7L2 expression by tissue microarray of 118 IHC-stained pancreatic cancer tissues from FUSCC." (PMID 29476053, 2018). "The impact of TCF7L2 on aerobic glycolysis was further confirmed in vivo by assessing 18FDG uptake in pancreatic cancer patients and in a subcutaneous xenograft mouse model." (PMID 29476053, 2018). "In conclusion, our present study revealed TCF7L2 as a novel predictive marker for prognosis of pancreatic cancer." (PMID 29476053, 2018). "To explore the impact of TCF7L2 on pancreatic cancer patient prognosis, we examined the expression of TCF7L2 in TCGA pancreatic cancer patients." (PMID 29476053, 2018). "The WNT pathway is often constitutively activated in human cancers, such as colon, liver, breast, and pancreatic cancer, with high upregulation of TCF7L2." (PMID 28499350, 2017).
pancreatic cancer (continued). "The effects of ICG-001 on PANC1 cells and comparison to gene expression patterns in TCF7L2 knockdown cells suggests that ICG-001 inhibits proliferation of pancreatic cancer cells via a mechanism different than the WNT pathway." (PMID 26191083, 2015). "Our findings suggest that the transcriptional activation of Gαi3 by TCF7L2 may serve as a critical mechanism for Gαi3 overexpression in pancreatic cancer." (PMID 39349432, 2024). "In pancreatic cancer, high TCF7L2 expression predicts a poor prognosis." (PMID 35864968, 2022). "Our mechanistic hypothesis is supported by gene expression data, showing that both AURKA and TCF7L2 are significantly overexpressed in pancreatic tumor tissues in comparison to healthy donors." (PMID 33578795, 2021). "In our present study, we identified TCF7L2 as a novel predictive marker for OS of pancreatic cancer patients, and we provided mechanisms for the metabolism effects, indicating a potential role for TCF7L2 in aerobic glycolysis regulation by targeting the EGLN2/HIF-1α axis." (PMID 29476053, 2018). "To further evaluate the function of TCF7L2 in pancreatic cancer viability and proliferation, we first generated two lentiviral particles targeting TCF7L2, termed pLKO.1-shTCF7L2-A and pLKO.1-TCF7L2-B, to mediate silencing of TCF7L2 in PANC-1 and MIA PaCa-2 cells." (PMID 29476053, 2018). "As shown, EGLN2 mRNA and protein levels increased in TCF7L2-silenced pancreatic cancer cells." (PMID 29476053, 2018). "Moreover, the OS for pancreatic cancer patients with higher TCF7L2 expression was significantly shorter than for patients with low TCF7L2 expression (P < 0.001, median survival time: 33.6 months vs. 17.1 months vs. 10.5 months vs. 6.2 months)." (PMID 29476053, 2018). "TCF7L2 was closely related with several glycolysis genes in common pancreatic cancer cell lines." (PMID 29476053, 2018). "Thus, we hypothesized that TCF7L2 may play an important role in the incidence or development of pancreatic cancer and could be closely related with prognosis in pancreatic cancer." (PMID 29476053, 2018). "This led us to assume that TCF7L2 might negatively regulate EGLN2 expression in pancreatic cancer." (PMID 29476053, 2018). "Thus, targeting the TCF7L2/β-catenin interaction might be a promising way to cut fuel supply for pancreatic cancer, since cancer cell metabolism has been proven to be a new target for improving cancer cell malignancies." (PMID 29476053, 2018). "ChIP assay results underscored an enhanced interaction between the TCF7L2 protein and the Gαi3 promoter region in both pancreatic cancer tissues and different cells, suggesting that this augmented binding may be a pivotal mechanism behind the upregulation of Gαi3 in pancreatic cancer." (PMID 39349432, 2024). "Collectively, our present study uncovered TCF7L2 and EGLN2 as novel prognostic markers for pancreatic cancer and provided a possible regulatory mechanism." (PMID 29476053, 2018). "The glycolytic process (extracellular acidification rate, ECAR) significantly decreased in TCF7L2-silenced PANC-1 and MIA PaCa-2 cells, which implied that TCF7L2 has a positive effect on the glycolysis rate in pancreatic cancer cells." (PMID 29476053, 2018). "Importantly, ChIP assay demonstrated a significant increase in the binding of TCF7L2 protein to the Gαi3 promoter region, as predicted in the JASPAR database, across various pancreatic cancer cells." (PMID 39349432, 2024). "Furthermore, we detected the expression status of TCF7L2 by IHC staining and analyzed its correlation with 18F-FDG uptake in pancreatic cancer patients." (PMID 29476053, 2018).
prostate carcinoma (15 papers, 2008 to 2024). A carcinoma that arises from epithelial cells of the prostate gland. "Men who are homozygotic for the TCF7L2‐rs12255372 T allele have a high relative risk for more aggressive prostate cancer, defined by a high Gleason score (OR = 1.7; 95% CI = 1.0–2.8) or by a high regional and/or distal stage (OR = 1.7; 95% CI = 1.1–2.6)." (PMID 34612510, 2022). "Even if the concentration of sex hormones and the expression of sex hormone receptors are among the main risk factors for a higher incidence of prostate cancer, carrying the TCF7L2 rs12255372‐T allele is associated with prostate cancer progression and metastases." (PMID 34612510, 2022). "For both promoters and enhancers we also identified a subset of disruptive variants that target response elements for factors of special interest to prostate cancer, namely AR, FOXA1, NKX3-1, TCF7L2, MYC, GATA1 and GATA3." (PMID 24497837, 2014). "Recent data has shown that TCF7L2 could activate PI3K/AKT pathway in numerous diseases, such as prostate cancer and T2DM, which might also explain why TCF7L2 confers so many functions in the incidence and development of metabolic diseases." (PMID 31312258, 2019).